BDNF (brain derived neurotrophic factor)
Diseases named in the same sentence as BDNF in open-access papers (continued):
Sharing a sentence is not in itself a finding about the gene and the disease.
depression (continued). "Other observations regarding anti-depression treatment provide additional supporting evidence for the roles of BDNF in mood disorders." (PMID 26091093, 2015). "In this study, we further demonstrated that the MAE ameliorated depression symptoms, especially in reducing crying, changes in appetite, and fatigue, and increased blood levels of BDNF." (PMID 26075212, 2015). "For instance, we found an association in the meta-regressions between severity of manic and depressive episodes, mostly in plasma, and in the within-group meta-analysis BDNF increased after treatment of a manic episode in plasma, but not in serum." (PMID 26621529, 2015). "Increased levels of BDNF has been reported following ECT, and BDNF has been suggested as a potential biomarker for depression." (PMID 25927716, 2015). "In human studies, quetiapine extended-release treatment (300 mg/day) for 16 weeks has been shown to increase BDNF levels in depression and to decrease levels in mania/mixed episodes." (PMID 25667608, 2015). "Recent reports have shown that pro-BDNF promotes neuronal death, spine retraction and hippocampal long-term depression, suggesting that pro-BDNF and BDNF exert opposing biological functions." (PMID 26151924, 2015). "For example, curcumin, a nonflavonoid phenolic compound present in Curcuma longa, known and used in Indian traditional medicine, after administration significantly decreased depression-like behaviour in rats probably through improvement of the BDNF level." (PMID 26180581, 2015). "Using multiple regression, serum BDNF was adjusted for the Hamilton depression rating scale (HDRS) and the VAS scores (r-squared = 0.07, standard β coefficients = −0.2 and −0.14, respectively, P < 0.001)." (PMID 25947167, 2015). "In the between-group meta-analyses, the results remained significant in depression when we assessed peripheral BDNF levels according to source (i.e. serum or plasma), and also remained non-significant in euthymia regardless of the source." (PMID 26621529, 2015). "BDNF levels in patients suffering from major depression disorders are significantly lower than control subjects." (PMID 26075212, 2015). "In humans, methylation of the BDNF gene promoter region has also been associated with the development of PTSD, depression, and other trauma-related disorders in children." (PMID 26649946, 2015). "The correlation between depression severity and BDNF levels in blood was previously studied on the whole spectrum of MDD patients with respect to HAM-D scores." (PMID 26010085, 2015). "In chronic mild stress models of depression, a single administration of ketamine confers a rapid and long-lasting antidepressant effect by increasing BDNF levels in the PFC and hippocampus." (PMID 26506052, 2015). "Among the 47 participants in the experimental group, 41 completed the program and pre- and posttest (depression questionnaire and blood BDNF levels)." (PMID 26075212, 2015). "In 2009, based on preliminary results, we proposed serum BDNF levels as a possible adjunctive tool to discriminate between bipolar and unipolar depression with a high accuracy of 0.95." (PMID 26621529, 2015). "Further studies of the gender effect on the correlation between BDNF and depression severity are warranted." (PMID 26010085, 2015). "In contrast, Pro-BDNF binds to p75 neurotrophin receptor to induce cell apoptosis and long-term depression." (PMID 26091093, 2015). "The major finding of this work is a significant positive correlation between blood BDNF levels and depression severity in untreated female patients with severe MDD determined by the HAM-D>24." (PMID 26010085, 2015). "In conclusion, our results indicate that common, functionally significant polymorphisms in BDNF and NTRK2 partially modulate stress-coping strategies, depression, and anxiety." (PMID 26445699, 2015). "The first three published found BDNF levels decreased in both mania and depression, with normal levels in euthymia." (PMID 26621529, 2015).
depression (continued). "Additional studies focused on the relationship of BDNF with the incidence and course of depression during the antepartum and postpartum periods are warranted." (PMID 25886523, 2015). "The regression analyses showed that the mean serum sortilin concentration increased significantly with increasing age, BMI, serum VEGF and serum BDNF levels and with high alcohol intake, depression and previous depressive episodes." (PMID 26556286, 2015). "In this review, the BDNF gene is the second most frequently studied gene in adolescents with depression." (PMID 26733829, 2015). "Recent studies have reported changes in serum BDNF levels in patients with psychiatric diseases, such as major depressive disorders." (PMID 25629040, 2015). "The statistical power calculations using G-Power for Mann-Whitney tests were based on the previous meta-analyses of BDNF and S100B alterations in major depression." (PMID 26500502, 2015). "Our final multiple regression model included five predictors: depression, serum BDNF, serum VEGF, alcohol intake and BMI." (PMID 26556286, 2015). "In summary, the 12-week MAE had a significant impact on the enhancement of BDNF levels and improvement of depression symptoms." (PMID 26075212, 2015). "We examined the expression of BDNF that is an attractive candidate protein for its potential involvement in the co-occurrence of SUD in depression." (PMID 25733538, 2015). "The downstream components of the BDNF signaling cascade, Ras–MAPK and PI3K-AKT, have been implicated in depression and treatment response." (PMID 26317356, 2015). "Given the role of BDNF–TrkB signaling in the depression-like phenotype, it is likely that both stereoisomers exert antidepressant effects by normalizing BDNF levels in the PFC and hippocampus (CA3 and DG), but not NAc." (PMID 26327690, 2015). "Mean serum BDNF levels in patients with mild, moderately severe and severe forms of depression were 41.7 ± 14.5 ng/ml, 36.4 ± 14.8 ng/ml, and 42.1 ± 11.1 ng/ml respectively." (PMID 25886523, 2015). "A significant interaction between BDNF Val66Met and life stress in depression was widely observed in adults." (PMID 26733829, 2015). "Brain derived neurotrophic factor (BDNF) has been shown to perform an important function in the pathophysiology of depression." (PMID 26641254, 2015). "Depression results from changes in various biochemical factors, including stress hormones, cytokines, neurotrophic factors such as brain-derived neurotrophic factor (BDNF), and neuropeptides such as orexins." (PMID 25884812, 2015). "The innate inflammatory cascade has been shown to increase glutamate neurotransmission, central sensitization, and excitotoxicity, reduce BDNF and neurogenesis, and activate neurodegenerative cascades, events observed in both depression and pain conditions." (PMID 26342110, 2015). "Decreased levels of BDNF in the serum have been related to the pathophysiology of depression, and this relationship is reinforced by the reversal of this condition by treatment with antidepressants." (PMID 25629040, 2015). "To build a model of the serum sortilin level, we used a stepwise forward inclusion and backward elimination procedure, and the final model contained five significant determinants: depression, serum BDNF, serum VEGF, alcohol and BMI." (PMID 26556286, 2015). "BDNF levels in the NAc of METH-treated mice were significantly higher than those of the control mice, suggesting that increased BDNF levels in the NAc are involved in the depression-like behavior after METH withdrawal." (PMID 26506052, 2015). "The brain derived neurotrophic factor-extracellular regulated protein kinase (BDNF-ERK/AKT-CREB) signaling cascade plays an important role in the pathophysiology of depression, and is critical for hippocampal neurogenesis." (PMID 25618406, 2015). "But while brain levels of BDNF are altered in depression and stress, evidence suggests a differential role of BDNF depending on the location in the brain." (PMID 25908105, 2015).
depression (continued). "We found a positive correlation between blood BDNF levels and severity of depression only among untreated women with severe MDD (HAM-D>24)." (PMID 26010085, 2015). "We found no specific effects of DHA on increased serum levels of BDNF and pro-BDNF; however, evidence in this study suggests that increased BDNF and pro-BDNF have a protective effect by minimizing depression severity." (PMID 26151924, 2015). "BDNF levels were moderately decreased in persons with BD during mania and largely decreased during depression." (PMID 26621529, 2015). "To examine differences in depression scores between genotypes, we entered BDNF, 5HTTLPR-rs25531, and C(-1019)G 5HT1a into separate GEE models that included time to account for repeated MADRS measures." (PMID 25781924, 2015). "Decreased BDNF levels have been identified in patients who have suffered from major depressive disorder, whereas patients who underwent successful antidepressant treatment have shown increased BDNF levels." (PMID 25810926, 2015). "Several lines of evidence suggest that brain-derived neurotrophic factor (BDNF) is involved in depression, such that the expression of BDNF is decreased in depressed patients." (PMID 26114099, 2015). "Lower levels of peripheral BDNF levels in manic and depressive episodes of BD were found in previous meta-analysis on the topic." (PMID 26621529, 2015). "We believe this is the largest study to investigate the role of BDNF epigenetics in depression and the first study to examine the relationship between BDNF methylation and depression using buccal-derived DNA." (PMID 26285129, 2015). "Acute and chronic stresses are reported to increase the risk of developing mood disorders, and several studies had showed the negative environmental stimuli effect on the relationship between BDNF and depression." (PMID 26091093, 2015). "The downregulation of the hippocampal BDNF expression has been demonstrated in various animal depression models and in depressed patients; the chronic treatment of several classes of antidepressants increases the BDNF expression." (PMID 26798520, 2015). "We found that the combination of music and exercise enhanced immunity, induced the release of beneficial hormones such as BDNF, and decreased depression symptoms." (PMID 26075212, 2015). "The results of this study showed that MAE improved depression symptoms and increased neurorelated hormones, such as BDNF in community dwelling women." (PMID 26075212, 2015). "Brain-derived neurotrophic factor (BDNF) and its specific receptor, tropomyosin-related kinase (TrkB), have a role the in pathophysiology of depression." (PMID 26506052, 2015). "Outcomes of studies on the relationship between BDNF and dopaminergic pathway and depression in adolescents." (PMID 26733829, 2015). "Conditional fetal, post-natal, hippocampal, and forebrain-inducible BDNF-KO mice displayed depression-like behaviors in certain tests." (PMID 25762938, 2015). "Series of clinical and basic studies have demonstrated that depression decreases BDNF expression which can be reversed or blocked by antidepressant treatment." (PMID 25821488, 2015). "Here, we firstly reported that a GO game ameliorated the depression by affecting the serum levels of BDNF." (PMID 26379544, 2015). "Nevertheless, various disruptions in the BDNF pathway do lead to both schizophrenia and depression-related behavioral deficits." (PMID 25762938, 2015). "There is accumulating evidence, primarily focused on postpartum period, showing decreased BDNF levels with the presence of depression." (PMID 25886523, 2015). "Considering known gender differences in depression, we analyzed BDNF/HAM-D correlation in untreated men and women with severe MDD (HAM-D≥24) separately." (PMID 26010085, 2015). "After adjusting for depression and pain, serum BDNF changed in the opposite direction of the clinical outcomes, which suggests that, the elevation of serum BDNF levels after EA is inversely proportional to the perceived pain." (PMID 25947167, 2015).
depression (continued). "As one of the largest epigenetic studies of depression, and the first investigating BDNF methylation in buccal tissue, our findings highlight the potential for buccal BDNF methylation to be a biomarker of depression." (PMID 26285129, 2015). "BDNF is the most abundant neurotrophin in the mammalian central nervous system, and reduced BDNF level in the hippocampus has been revealed to be related to the onset of depression." (PMID 26733829, 2015). "Parsing the differences that lead to specific disruptions in behavior will greatly aid in elucidating the contributions of the BDNF pathway to depression and schizophrenia." (PMID 25762938, 2015). "The correlation between BDNF blood levels and depression severity in females was markedly stronger than in the mixed group." (PMID 26010085, 2015). "Resveratrol, a non-flavonoid polyphenol antioxidant extracted from red grapes, also showed antidepressant effects in an animal model of depression by restoring the expressions of brain-derived neurotrophic factor (BDNF) in both hippocampus and frontal cortex." (PMID 26633366, 2015). "Recently, exercise has been shown to increase brain-derived neurotrophic factor (BDNF) in aged women; moreover, exercise has been also shown to increase BDNF levels in aged women with recurring major depression." (PMID 26075212, 2015). "Emerging pieces of evidence suggest that alterations of brain-derived neurotrophic factor (BDNF) expression play an important role in depression." (PMID 25739024, 2015). "EA modulation of pain and BDNF occurs according to the CNS situation at the moment of its administration, as it was related to depression and the timing of its administration." (PMID 25947167, 2015). "In brief, lower BDNF levels in serum and plasma have been reported in depression and BDNF levels seem to normalise levels in periods of remission." (PMID 26011424, 2015). "In fact, changes in BDNF and subsequent alterations in synaptic plasticity have been shown to contribute to both pain and depression." (PMID 26260027, 2015). "Analysis of severe depression cases (HAM-D>24) showed a trend for correlation between baseline BDNF levels and HAM-D scores (p = 0.0646, n = 43)." (PMID 26010085, 2015). "Recent studies have demonstrated that proBDNF and mature BDNF facilitate long-term depression and long-term potentiation, respectively, implying opposing cellular functions." (PMID 25886523, 2015). "BDNF has been found to be lower in subjects with other brain based disorders and mental illness such as major depressive disorder and bipolar disorder." (PMID 26866045, 2015). "Our findings further confirmed the therapeutic effect of TFF3 against depression and suggested that the normalization of the BDNF-ERK-CREB pathway was involved in the behavioral response of TFF3 for the treatment of depression." (PMID 26633367, 2015). "BDNF has previously been investigated not only for its brain plasticity modulating effect in dementia patients, but also in subjects with depression and in animal studies, high-intensity exercise has a modulating effect on BDNF." (PMID 26379621, 2015). "Several clinical studies show that blood brain-derived neurotrophic factor (BDNF) levels are reduced in Alzheimer’s disease, mild cognitive impairment, and major depressive disorder." (PMID 25659147, 2015). "In summary, the results of this study indicate the potential for AGN to effectively treat CORT-related depression and anxiety-like symptoms, possibly via modulation of the central noradrenergic system and regulation of BDNF expression." (PMID 26138544, 2015). "Overall, we found that pregnant women with lower early pregnancy serum BDNF levels, a well-studied neurotropic peptide, had higher odds of antepartum depression as compared with their counterparts who had higher levels." (PMID 25886523, 2015).
depression (continued). "Lower BDNF level was observed in individuals with depression and in post-mortem brain of suicide victims with major depression (40%) or other psychiatric disorders." (PMID 26175754, 2015). "Most of these studies have suggested peripheral BDNF as a state-marker in BD, with decreased levels in mania and depression returning to normal in euthymia, and also being correlated with severity of mania and depression." (PMID 26621529, 2015). "Most attractive was the report that both miRNAs targeted BDNF, which have also been detected at lower serum levels in patients with depression." (PMID 26733805, 2015). "For BDNF, the percentage of methylation in one region was significantly higher in participants with anxiety/depression compared to control participants (t-test p= 0.0026; Wilcoxon–MannWhitney test p = 0.0001)." (PMID 26175754, 2015). "The relationship between decreased BDNF levels and the pathophysiology of depression is supported by several reports." (PMID 25629040, 2015). "Since watching TV is not a comparative activity, further studies should define a better design to simultaneously compare the effects of exercise, music, and their combination on the improvement of depression and changes of BDNF levels." (PMID 26075212, 2015). "A growing body of evidence from both postmortem and animal studies demonstrates that BDNF and its receptor, tropomyosin-related kinase B (TrkB), are involved in the pathophysiology and treatment of depression." (PMID 26633367, 2015). "In this study we observed a higher methylation of BDNF in older women with anxiety disorders/depression." (PMID 26175754, 2015). "There is accumulating evidence for the role of brain-derived neurotrophic factor (BDNF) in the pathophysiology of depression." (PMID 25886523, 2015). "Accordingly, the BDNF gene appears to be a potential candidate mediator of mechanisms relevant to the pathogenesis of depression." (PMID 25821488, 2015). "Converging evidence now strongly implies that deficits in BDNF signalling contribute to the pathogenesis of several major diseases and disorders, such as Huntington’s disease, Alzheimer’s disease, and depression." (PMID 26437780, 2015). "Patients with depression have been shown to have reduced levels of brain-derived neurotrophic factor (BDNF), a key neurotrophin relevant for hippocampal neurogenesis." (PMID 26037484, 2015). "To fulfill this translational aim, we first will pool the preclinical literature on the relationships between ECS, BDNF and depression-like behavior." (PMID 26529101, 2015). "Recent evidence suggests that neuronal plasticity plays an important role in the recovery from depression and brain derived-neurotrophic factor (BDNF) is a mediator of this plasticity (Castrén and Rantamäki, 2010)." (PMID 26733805, 2015). "Middle-aged community women are encouraged to exercise moderately to improve their depression symptoms and BDNF levels." (PMID 26075212, 2015). "The results indicated that older women with anxiety disorders/depression differed on BDNF DNA methylation level from the women in the control group, particularly for the CT carriers." (PMID 26175754, 2015). "Decreased BDNF levels have been consistently reported in depression, particularly in suicidal patients." (PMID 25762938, 2015). "The most important finding of this study is a positive correlation between serum BDNF levels and depression severity in women with severe MDD (HAM-D≥24)." (PMID 26010085, 2015). "Longitudinal data with serial measures of BDNF levels and assessments of depressive disorders during pregnancy and the postpartum periods of pregnancy are warranted." (PMID 25886523, 2015). "We believe that the modifying effect of gender and depression severity (evaluated by the HAM-D scale) can explain a controversy between previous studies of the relationship between BDNF levels and disease severity in untreated MDD patients." (PMID 26010085, 2015).